MOS (MOS proto-oncogene, serine/threonine kinase)
Description:
Serine/threonine kinase involved in the regulation of MAPK signaling. Is an activator of the ERK1/2 signaling cascade playing an essential role in the stimulation of oocyte maturation.
Synonyms: MSV; OZEMA20
Tractability: Small molecule: it belongs to a druggable protein family.
Target class: Other protein kinase MOS family; Other protein kinase group; Protein Kinase; Kinase; Enzyme
Gene: Protein-coding gene on chromosome 8 (56,112,942 to 56,113,982, reverse strand). Ensembl gene ENSG00000172680.
Subcellular location: Cytoplasm
Gene Ontology:
Molecular function: protein binding; MAP kinase kinase kinase activity; protein serine/threonine kinase activity; ATP binding; protein kinase activity; protein serine kinase activity
Biological process: oocyte maturation; positive regulation of ERK1 and ERK2 cascade; chromatin organization; establishment of meiotic spindle orientation; MAPK cascade; meiotic spindle organization; negative regulation of metaphase/anaphase transition of meiotic cell cycle; positive regulation of MAPK cascade
Cellular component: cytoplasm
Genetic constraint (gnomAD): Loss-of-function variants: 1 observed, 0.13 expected, observed/expected ratio (o/e) 7.72. That is too few expected variants to judge how well the gene tolerates losing a copy. Missense variants: 419 observed, 473.98 expected, observed/expected ratio (o/e) 0.88, 90% interval 0.81 to 0.96. Synonymous variants: 190 observed, 215.47 expected, observed/expected ratio (o/e) 0.88, 90% interval 0.78 to 1.
Homologues: Orthologues: chimpanzee MOS (99% identical), macaque MOS (97% identical), dog MOS (83% identical), rabbit MOS (81% identical), pig MOS (79% identical), guinea pig MOS (77% identical), mouse Mos (73% identical), rat Mos (73% identical), zebrafish mos (47% identical), Drosophila melanogaster Mos (26% identical), Caenorhabditis elegans Y53F4B.1 (20% identical). Paralogues in human: MAP3K10 (23% identical), MAP3K21 (23% identical), MAP3K9 (22% identical), TESK1 (22% identical), TNNI3K (22% identical), MAP3K13 (21% identical), MAP3K11 (21% identical), MAP3K12 (21% identical), LIMK1 (21% identical), BRAF (20% identical), LRRK2 (20% identical), LIMK2 (20% identical), and 11 more.
Diseases named in the same sentence as MOS in open-access papers:
MOS is named in the same sentence as 16 diseases in open-access papers, as found by Europe PMC text mining. Sharing a sentence is not in itself a finding about the gene and the disease. The quoted sentences say what the papers report.
lymphoma (2 papers, 2006 to 2022). A malignant (clonal) proliferation of B- lymphocytes or T- lymphocytes which involves the lymph nodes, bone marrow and/or extranodal sites.
cervical cancer (1 paper, 2013). A primary or metastatic malignant neoplasm involving the cervix. "In addition, ectopic expression of some key meiotic genes was also reported in primary tumours, for example MOS in NSCLC, DMC1 in cervical cancer, SPO11, REC8, SGO1 and HORMAD1 in melanoma." (PMID 24025698, 2013).
colorectal cancer (1 paper, 2024). A primary or metastatic malignant neoplasm that affects the colon or rectum. "Within the top five genes based on WRF (Ensemble 1 and Ensemble 2), SLC30A3, MOS, C1ORF61, and MBL1P genes were found to have an association with CRC, gene PAGE2, a gene from cancer-germline genes, was found to be upregulated in Caco-2 colorectal cancer cell line." (PMID 39897528, 2024).
Infertility (1 paper, 2025). "Recent clinical research has indicated that women with biallelic mutations in the MOS gene experience infertility due to early embryonic arrest." (PMID 39764564, 2025).
myeloid malignancies (1 paper, 2009). "As well as genes predominantly methylated in certain HN subtypes, we also identified six genes, i.e. DBC1, DIO3, FZD9, HS3ST2, MOS and MYOD1, that were significantly hypermethylated in B-cell, T-cell and myeloid malignancies." (PMID 19750229, 2009). "As well as identifying genes showing aberrant DNA methylation in certain HN subtypes, we also detected six genes—DBC1, DIO3, FZD9, HS3ST2, MOS, and MYOD1—that were significantly hypermethylated in B-cell, T-cell, and myeloid malignancies." (PMID 19750229, 2009).
ovarian carcinoma (1 paper, 2006). A malignant neoplasm originating from the surface ovarian epithelium. "It should also be noted that up-regulation of MOS protein has been previously shown in human ovarian cancer cells arrested at the spindle checkpoint by microtubule-damaging agents." (PMID 16401344, 2006).
thymoma (1 paper, 2016). A neoplasm arising from the epithelial cells of the thymus. "On the other hand, MoS may be associated with several tumors, of which thymoma is the most common." (PMID 27247812, 2016).
tumor (3 papers, 2018 to 2024). "While EDNRB and FMN2 as well as TBXT and ZNF671 could have potential tumor suppressor functions, MOS is a well-known oncogene." (PMID 38643219, 2024).
MOS also shares sentences with these, for which no sentence is quoted: cancer (4 papers); gastric cancer (3); B-cell lymphomas (1); female infertility (1); lung carcinoma (1); ovarian tumors (1); prostate carcinoma (1); T-cell lymphomas (1).